MMP12 (matrix metallopeptidase 12)
Diseases named in the same sentence as MMP12 in open-access papers (continued):
Sharing a sentence is not in itself a finding about the gene and the disease.
periodontitis (continued). "In the gingival tissue of patients with chronic periodontitis, the expression of MMP-12 in CD64-derived monocytes increased significantly, and the expression of surface costimulatory molecule, CD200R, decreased, resulting in irreversible tissue decline and immune activation disorders." (PMID 36212719, 2022). "Furthermore, lack of association between these variants and periodontitis may also suggest that an increase in the MMP-12 or MMP-13 transcriptions may not necessarily lead to an increase in the destructive effect of these enzymes on the periodontal tissues." (PMID 27194818, 2016). "We present high levels of MMP-12 and low levels of EGF and OLR-1 as interesting candidates that should be further validated in additional cohorts for potential to serve as biomarkers for severe periodontitis." (PMID 39101637, 2024). "As of today, the role of MMP-12 in periodontitis is not understood." (PMID 39101637, 2024). "In addition to this, MMP-1, MMP-2, MMP-10, and MMP-12 were also observed to be significantly increased in patients with OSCC compared to healthy patients and patients with benign oral masses (OBM) and mild chronic periodontitis (CPD)." (PMID 33892690, 2021).
squamous cell carcinoma (7 papers, 2005 to 2024). A carcinoma arising from squamous epithelial cells. "Exceptions (phet < 0.05) included CEACAM5, which was more strongly associated with adenocarcinoma than squamous cell carcinoma, and MMP12, which was more strongly associated with squamous cell carcinoma than with adenocarcinoma." (PMID 37264016, 2023). "In a squamous-cell carcinoma study, MMP12 had a dual role in tumor progression." (PMID 31119098, 2019). "Among these, MMP12, AURKB, SERPINE1, and MMP1 have been confirmed to play important roles in squamous cell carcinoma including LSCC." (PMID 33680908, 2020). "In fact, some studies have shown that the expression level of MMP-12 derived from cancer cells was higher in aggressive and poorly differentiated squamous cell carcinoma, while macrophage-derived MMP-12 was not abundant in early-stage cancer." (PMID 24531055, 2014). "In oral verrucous and squamous cell cancer, the absence of MMP12 from epithelial cells has been reported to be a marker of good prognosis in non-invasive oral carcinoma." (PMID 15989693, 2005).
coronary artery disease (6 papers, 2011 to 2022). "While all mice harboured coronary disease, atherosclerotic burden was reduced in Mmp7-deficient and Mmp12-deficient mice and increased in Timp1-deficient animals, compared to relevant controls." (PMID 34848763, 2021). "Plasma MMP-12 levels are increased in patients with coronary artery disease and may, therefore, be an independent risk factor for coronary artery disease." (PMID 21887284, 2011).
esophageal squamous cell carcinoma (6 papers, 2010 to 2025). Esophageal squamous cell carcinoma (ESCC) is a type of esophageal carcinoma (EC) that can affect any part of the esophagus, but is usually located in the upper or middle third. "The overexpression of MMP1 and MMP12 have been associated with the development of tumors in other anatomical regions, including esophageal SCC and head and neck SCC (HNSCC)." (PMID 34638231, 2021). "In particular, MMP12 expression is elevated in squamous carcinomas at other anatomical sites, such as esophageal squamous cell carcinoma (ESCC) and oral squamous cell carcinoma (OSCC)." (PMID 37601247, 2023). "In addition to this, high expression of MMP-12 was observed in esophageal squamous cell carcinoma compared to normal epithelial cells." (PMID 33892690, 2021).
Hypertension (6 papers, 2011 to 2023). The presence of chronic increased pressure in the systemic arterial system. "Likewise, MMP12 was associated with DM [OR (95%CI) = 1.56 (1.13–2.15), p = 0.007] and hypertension [OR (95%CI) = 1.56 (1.12–2.17), p = 0.008]." (PMID 34062730, 2021). "Interestingly, elevated 20-HETE was previously associated with arterial stiffness and systolic hypertension in a murine model of hypertension with metabolic syndrome via matrix metalloproteinase 12 (MMP12) activation." (PMID 36144261, 2022).
Insulin resistance (6 papers, 2021 to 2025). Increased resistance towards insulin, that is, diminished effectiveness of insulin in reducing blood glucose levels. "MMP12 was described as a negative regulator of glucose metabolism, causing mitochondrial dysfunction and insulin resistance in vitro in adipocytes from Western-type diet-fed mice." (PMID 41308745, 2025). "In humans, MMP12+ macrophages signature in the WAT is also associated with insulin resistance in obese subjects." (PMID 37445827, 2023). "Since WAT dysfunction plays a crucial role in the development of systemic insulin resistance and the onset of CMDs, we further investigated whether the genetic deficiency of MMP12 leads to morphological and/or functional changes in this tissue." (PMID 38017481, 2023). "In agreement with our findings in BAT, a previous study reported that macrophage-produced MMP12 targets white adipocytes, leading to mitochondrial damage, inflammation, and insulin resistance." (PMID 41308745, 2025). "In humans, MMP-12+ macrophages signature in the white adipose tissue (WAT) was associated with inflammation and insulin resistance." (PMID 38541059, 2024). "This study showed that HFHS-induced MMP12 in the adipose tissue bridges microbiota-dependent adipose tissue inflammation and insulin resistance." (PMID 37445827, 2023). "Recently, the role of MMP12 has been investigated in microbiota-dependent metabolic alterations and insulin resistance in mice and obese patients." (PMID 37445827, 2023). "Researchers at the University of Washington confirmed that MMP12 regulates insulin sensitivity and is positively correlated with insulin resistance." (PMID 34863141, 2021). "Recent observations suggest that that increased expression of MMP-12 by M2 macrophages in adipose tissue of obese subjects may be a compensatory mechanism to restrain adipose tissue expansion and insulin resistance." (PMID 38541059, 2024). "Interestingly, MMP12 treatment of adipocytes provokes insulin resistance, whereas treatment with the MMP12 inhibitor MMP408 reduces fasting glycemia and improves glucose tolerance in HFHS diabetic mice in the presence of microbiota." (PMID 37445827, 2023). "MMP12 was shown to be induced by HFHS in macrophages through a MYD88-ATF3–dependent pathway, yet more efforts are needed to deepen our understanding of the molecular mechanisms underlying MMP12-mediated insulin resistance." (PMID 37445827, 2023). "Moreover, Jung-Ting Lee proposed that MMP12 expression significantly promotes insulin resistance and that insulin were regulated by resident macrophages." (PMID 34863141, 2021). "On the other hand, MMP-12 expressing macrophages presented M2 anti-inflammatory phenotype which might serve as a compensatory mechanism to restrain adipose tissue expansion and insulin resistance." (PMID 38541059, 2024). "These macrophages exhibited a specific molecular signature that was associated with insulin resistance in obese patients and released MMP12, which acts as a bridge between inflammation and mitochondrial damage in WAT, ultimately leading to insulin resistance." (PMID 37842639, 2023). "Consistently, MMP12−/− conventional mice, but not germ-free MMP12−/− animals, exhibit improved insulin resistance compared to WT mice, confirming the important role of MMP12 in mediating intestinal microbiota-induced metabolic alterations in T2D." (PMID 37445827, 2023). "In addition, our other data supports that knocking out MMP12 in ApcMin/+ mice may reduce insulin levels or increase insulin sensitivity, which could contribute to reversing insulin resistance, while it was not related to the basic function of islets based on results of H&E staining and IHC staining." (PMID 34863141, 2021).
metastatic disease (6 papers, 2012 to 2023). "MMP-12 levels have been correlated with local recurrence and metastatic disease." (PMID 22509397, 2012). "MMP7, MMP13, and MMP10 were upregulated, and MMP12 and MMP9 were downregulated in metastatic tumours compared with nonmetastatic tumours." (PMID 31996191, 2020).
preeclampsia (6 papers, 2021 to 2024). Preeclampsia is a hypertensive disorder of pregnancy that is characterized by new-onset hypertension with proteinuria presenting after 20 weeks of gestation, and depending on mild or severe forms may initially present with severe headache, visual disturbances, and hyperreflexia. "This study adds information on the association between decreased MMP-12 levels in early mid-pregnancy and later development of preeclampsia." (PMID 38253981, 2024). "PCOS women are at an increased risk of developing preeclampsia, a condition that shares common cardiovascular markers, such as MMP12." (PMID 39858399, 2024). "The pathophysiological background for the association between MMP-12 and preeclampsia development is unknown." (PMID 38253981, 2024). "Therefore, we suspect that our finding of an association between decreased MMP-12 in early mid-pregnancy and subsequent preeclampsia would have been even stronger if the blood samples had been collected in the first trimester." (PMID 38253981, 2024). "Adjusted logistic regression models showed an increased risk for later development of preeclampsia with decreasing levels of the following three biomarkers: MMP-12 (aOR 0.63, 95% CI 0.48–0.82), BNP (aOR 0.57, 95% CI 0.43–0.74), and PlGF (aOR 0.52, 95% CI 0.38–0.71)." (PMID 38253981, 2024). "The biomarkers that were associated with late-onset preeclampsia were BNP, MMP-12, alpha-L-iduronidase (IDUA), PlGF, low-affinity immunoglobulin gamma Fc region receptor II-b, and T cell surface glycoprotein." (PMID 38253981, 2024). "In particular, MMP-12 is highlighted as a promising predictive mid-pregnancy biomarker for subsequent preeclampsia." (PMID 38253981, 2024). "Downregulation of MMP-12 gene expression has been reported in first-trimester placentas of women who later develop preeclampsia, but also in term placentas of obese women indicating impaired placental development." (PMID 36180668, 2023). "Although other MMPs are known to be dysregulated in preterm preeclampsia, the focus on MMP-12 was due to its critical role in inflammation-mediated activity." (PMID 34195300, 2021). "We show enhanced MMP-12 expression in the placenta tissue of preterm preeclampsia reinforcing this notion." (PMID 34195300, 2021). "Interestingly, they found an increase of MMP-12 between the first and second (22–24 weeks) trimester in women with subsequent preeclampsia." (PMID 38253981, 2024). "However, further knowledge of the MMP-12 and other MMPs regarding pathophysiology and predictive accuracy in preeclampsia is needed." (PMID 38253981, 2024). "However, a recent study found lower levels of MMP-12 during gestational weeks 11–13 in women who later developed preeclampsia, than were found in those who continued to have a normotensive pregnancy." (PMID 38253981, 2024). "Our results suggest that MMP-12 is a promising novel preeclampsia biomarker." (PMID 38253981, 2024). "In conclusion, the results of the present study of cardiovascular biomarkers and their individual importance for prediction of preeclampsia found MMP-12 to be the most promising candidate, but we also highlight BNP and IDUA as potential predictors for late-onset preeclampsia." (PMID 38253981, 2024).
psoriasis (6 papers, 2015 to 2026). An autoimmune condition characterized by red, well-delineated plaques with silvery scales that are usually on the extensor surfaces and scalp. "The network pharmacology results revealed that the primary targets of the active ingredients in STT were S100A9, GM2A, REN, MMP12, and RBP4, all of which were primarily associated with psoriasis." (PMID 37653756, 2023). "The network pharmacology results revealed that the key targets of active STT components, namely GM2A, REN, MMP12, RBP4, and S100A9, are primarily associated with psoriasis, potentially serving as the basis for the therapeutic effectiveness of STT." (PMID 37653756, 2023). "We found that MMP2, MMP12, MMP13, TIMP2, and TIMP4 distinguished psoriasis from psoriatic arthritis patients undergoing a systemic treatment, with a good diagnostic accuracy (Area under the ROC Curve (AUC) > 0.7)." (PMID 31717649, 2019). "A set of biomarkers, composed matrix metalloproteinases, and their tissue inhibitors comprises MMP2, MMP12, MMP13, TIMP2, and TIMP4 whose circulating levels are higher psoriasis undergoing systemic therapy compared to the parallel with psoriatic arthritis cohort." (PMID 34715781, 2021).
rheumatoid arthritis (6 papers, 2013 to 2025). A chronic, systemic autoimmune disorder characterized by inflammation in the synovial membranes and articular surfaces. "MMP12 expression is increased in rheumatoid arthritis synovial tissues and synovial fluids, implying that this protein is associated with the aetiology of RA." (PMID 36902078, 2023). "Immune pathways were also enriched: Role of Osteoclasts in Rheumatoid Arthritis (FDR = 5.88 × 10−3; MMP12, ADAM9, NFKBIA), T-cell receptor and Interleukin-1 signaling (both FDR = 8.83 × 10−3; NFKBIA, PSME3)." (PMID 41465234, 2025). "Here the authors show that MMP12 expression is reduced in patients with SLE and that MMP12 post-translationally truncates IFN-y, inhibiting its function and affecting pathogenesis of mouse models of peritonitis, SLE and rheumatoid arthritis." (PMID 29925830, 2018). "Furthermore, MMP12 was discovered in human rheumatoid arthritis (RA) osteoclasts." (PMID 36902078, 2023).
aortic aneurysm (5 papers, 2012 to 2022). A ruptured aneurysm located in the wall of the proximal portion of the descending aorta proceeding from the arch of the aorta. "In agreement with this, several studies reported an increased expression and activity of MMP-1, MMP-2, MMP-3, MMP-9, and MMP-12 in aortic aneurysm tissues." (PMID 35456498, 2022).
Bladder cancer (5 papers, 2015 to 2025). "Consistent with a previous report in other tumors, increased MMP12 expression alone was also sufficient to cause bladder cancer cell invasion and migration." (PMID 39557851, 2024). "In conclusion, aberrant RON expression in bladder cancer cells and MMP12 and HIF-2α activities form a functional axis that causes increased bladder cancer cell migration and invasion." (PMID 39557851, 2024). "Taken together, these results suggest the presence of a potential signaling and functional axis among RON, HIF-2α, and MMP12 in the bladder cancer cells, which coordinately regulate bladder cancer cell migration and matrix invasion." (PMID 39557851, 2024). "Other studies have shown that IL–20 upregulated invasion-related genes like MMP–9 and MMP–12, which degrade extracellular matrix in breast and bladder cancers." (PMID 26440411, 2015). "MMP12 was identified as directly regulated by RON in bladder cancer." (PMID 40282397, 2025). "The identification of the hsa-miR-659-3p/RON and RON/JNK/HIF-2α/MMP12 pathways offer valuable insights into the pathogenesis of bladder cancer and may serve as potential targets for therapeutic interventions in the management of this disease." (PMID 39557851, 2024). "Consequently, the activated JNK pathway increased MMP12 expression, ultimately driving bladder cancer cell migration and invasion." (PMID 39557851, 2024). "Furthermore, dysregulated RON has been implicated in the modulation of MMP12 expression through the activation of the JNK/HIF-2α signaling pathway, resulting in increased migration and invasion of bladder cancer cells." (PMID 39557851, 2024). "To elucidate the cellular relationships between RON and MMP12 in promoting bladder cancer cell invasive growth, we first study whether RON is physically in interaction with MMP12." (PMID 39557851, 2024). "Identification of MMP12 prompted us to study whether RON-mediated bladder cancer cell invasive growth is channeled through this functional protein." (PMID 39557851, 2024). "Moreover, Inhibition of MMP12 expression appeared to attenuate the RON-induced bladder cancer cell migration and invasiveness." (PMID 39557851, 2024). "Using two human urinary bladder cancer cell lines with either RON short hairpin knockdown or RON overexpression, the authors demonstrated that MMP12 and HIF2-α were expressed downstream of RON activation of ERK/JNK signaling." (PMID 40282397, 2025). "MMP12 and HIF-2α are the downstream effector molecules of RON, which are highly involved in RON-mediated bladder cancer cell migration and invasiveness." (PMID 39557851, 2024). "Results from mRNA sequencing and transcriptome analysis further demonstrated that MMP12, a downstream molecule of RON, is functionally involved in regulating RON-mediated bladder cancer cell migration and invasiveness." (PMID 39557851, 2024). "Our initial findings revealed that the downregulation of MMP12 effectively suppresses the cellular invasion and migration induced by RON overexpression in bladder cancer cells." (PMID 39557851, 2024). "Moreover, MMP2, MMP9, MMP12, and MMP16-enriched KEGG pathways include “Bladder cancer, endocrine resistance, and relaxin signaling pathway”, etc.." (PMID 38560573, 2024). "Moreover, MMP9, MMP12, MMP14, and MMP16-enriched KEGG pathways include “Bladder cancer, endocrine resistance, and relaxin signaling pathway” etc.." (PMID 39493455, 2024). "Since HIF-2α is a direct transcription factor for MMP12 and can be regulated by various types of kinase-independent of oxygen, we hypothesized that increased MMP12 expression in RON-overexpressing bladder cancer cells is mediated by RON-directed HIF-2α expression." (PMID 39557851, 2024). "Again, the MMP12 overexpression in these cells led to visible cell morphological alterations, although the changes were not as obvious as those observed in RON-overexpressing bladder cancer cells." (PMID 39557851, 2024).
Cerebral ischemia (5 papers, 2015 to 2025). Restriction of arterial blood supply to the brain associated with insufficient oxygenation to support the metabolic requirements of the tissue. "MMP-12 upregulation has also been associated with brain ischemia in animal models, with post-ischemic induction higher for MMP-12 than for any other MMPs." (PMID 36554397, 2022). "In this study, MMP-12 suppression corrected the myelin-associated abnormalities that occurred after cerebral ischemia and reperfusion." (PMID 25955565, 2015). "One previous study revealed the role of MMP12 in poststroke pathogenesis, particularly in the mechanisms of blood–brain barrier disruption, inflammation, apoptosis, and demyelination following cerebral ischemia and reperfusion." (PMID 40923186, 2025). "Other studies have demonstrated that MMP-12 induces brain injury by damaging the BBB after focal cerebral ischemia, while MMP-12 knockdown attenuates this effect." (PMID 36554397, 2022). "Recent reports have revealed that MMP-12 suppression can improve neurological outcomes in animal models of brain ischemia, making MMP-12 a promising therapeutic target." (PMID 36554397, 2022). "Both MMP-8 and MMP-12 have been reported as critical factors for brain damage in cerebral ischemia in animal studies." (PMID 30777092, 2019). "Indeed, MMP-12 induces BBB damage after cerebral ischemia and its levels are elevated after ICH in rodent models, which has a negative impact on sensorimotor function." (PMID 39069622, 2024). "Inhibition of apoptosis in the ipsilateral brain regions could be one of the major mechanisms of protection after MMP-12 knockdown subsequent to cerebral ischemia and reperfusion." (PMID 25955565, 2015).